HCG18 (HLA complex group 18)
Diseases named in the same sentence as HCG18 in open-access papers (continued):
Sharing a sentence is not in itself a finding about the gene and the disease.
myasthenia gravis (2 papers, 2021 to 2024). Myasthenia gravis (MG) is a rare, clinically heterogeneous, autoimmune disorder of the neuromuscular junction characterized by fatigable weakness of voluntary muscles. "HCG18 has been discussed in myasthenia gravis, osteoporosis, acute kidney injury after ischemia, nonalcoholic fatty liver disease, and many other diseases." (PMID 38627703, 2024).
osteoporosis (2 papers, 2020 to 2024). A condition of reduced bone mass, with decreased cortical thickness and a decrease in the number and size of the trabeculae of cancellous bone (but normal chemical composition), resulting in increased fracture incidence. "Therefore, we hypothesized that HCG18 might cause abnormal osteogenic differentiation of BMSCs through the miR-30a-5p/Notch1 axis, inhibiting its mediated bone formation and causing osteoporosis." (PMID 33176682, 2020). "However, it is unclear whether lncRNA HCG18 is involved in osteoporosis (OP)." (PMID 33176682, 2020).
anaplastic gliomas (1 paper, 2021). "In addition, HCG18 was identified as an immune-related signature and showed prognostic efficacy for anaplastic gliomas." (PMID 34222227, 2021).
COVID-19 (1 paper, 2023). A disease caused by infection with severe acute respiratory syndrome coronavirus 2. "In the PBMCs of COVID-19 patients, we found that the expression of all three HCG18 transcripts decreased according to disease severity and outcome." (PMID 37884975, 2023). "At the tissue level, HCG18 was readily detectable in heart and kidney tissues from COVID-19-affected patients; cardiomyocyte and vascular endothelial cells expressed moderate levels of HCG18." (PMID 37884975, 2023). "Similarly, in another study performed on a limited number of COVID-19 patients and controls, the expression of HCG18 was lower in the plasma of both mild and severe patients compared to the healthy controls." (PMID 37884975, 2023). "We found that also the expression levels of longer HCG18 transcripts were significantly down-modulated in non-surviving and critical COVID-19 patients." (PMID 37884975, 2023).
endometrial cancer (1 paper, 2021). Primary or metastatic malignant neoplasm involving the endometrium (mucous membrane that lines the endometrial cavity). "HCG18 showed potential effects on pathways in cancer, non-small cell lung cancer, endometrial cancer, and mTOR signaling pathway." (PMID 34615480, 2021).
hypospadias (1 paper, 2024). Hypospadias is the displacement of the urethral meatus on the ventrum of the penis. "Among them, HCG18 was the only lncRNA with high expression in bone marrow-derived MSCs and low expression in hypospadias." (PMID 38627703, 2024). "HCG18 is the only lncRNA with high expression in bone marrow-derived MSCs and low expression in hypospadias." (PMID 38627703, 2024). "Hence, it can be speculated that lncRNA HCG18 may affect the occurrence and development of hypospadias through post-transcriptional ceRNA regulation mechanisms." (PMID 38627703, 2024). "However, it remains unclear about the specific mechanism of HCG18 in the regulatory network of hypospadias." (PMID 38627703, 2024). "MSC-Exo-derived lncRNA HCG18 can enter target cells, and it may be involved in the regulation of EMT in hypospadias through the ceRNA network." (PMID 38627703, 2024).
Insulin resistance (1 paper, 2022). Increased resistance towards insulin, that is, diminished effectiveness of insulin in reducing blood glucose levels. "Additionally, HCG18 and BPLN3P are upregulated, which increases the risk of insulin resistance and type 1 diabetes, respectively." (PMID 36316461, 2022).
invasive ductal carcinoma (1 paper, 2021). "Association HCG18 expression and patients’ clinicopathological characteristics in invasive ductal carcinoma tissues." (PMID 34976998, 2021).
liver steatosis (1 paper, 2025). "Interestingly, many of them present the involvement of this molecule in liver steatosis by affecting the function of stellate cells or the expression of HCG18 in NAFLD patients." (PMID 39857813, 2025).
ovarian carcinoma (1 paper, 2022). A malignant neoplasm originating from the surface ovarian epithelium. "Although long noncoding RNA HLA complex group 18 (lncRNA HCG18) has been suggested to regulate cell growth in several tumours, the function of HCG18 in epithelial ovarian cancer (EOC) and its mechanism are still unclear." (PMID 34983361, 2022). "Moreover, expression levels of miR-152 were found to be dysregulated in ovarian cancer in previous studies, indicating a potential role of HCG18 in ovarian cancer." (PMID 34983361, 2022).
virus infection (1 paper, 2017). "Restore of TRAF6 expression by virus infection reserved the effect of HCG18 on the NP cells." (PMID 29038477, 2017). "Furthermore, HCG18-induced macrophage invasion and osteogenic differentiation were suppressed due to TRAF6 interfering virus infection." (PMID 29038477, 2017). "To investigate whether HCG18 exerts its biological effect by modulating the miR-146a-5p/TRAF6/NFκB axis, we repressed or restored the TRAF6 expression by TRAF6 overexpressing or interfering virus infection in NP cells." (PMID 29038477, 2017).
tumor (24 papers, 2020 to 2025). "We speculated that HCG18 could affect the activity of cancer-associated fibroblasts and promote tumour development by affecting the tumour microenvironment." (PMID 34983361, 2022). "Our research is consistent with the previous report, which reveals that HCG18 expression in GC tissues was remarkably higher than normal paracancerous tissues, and highly expressed HCG18 was strongly linked to a larger tumor size, lymph node IVS, and distal MTS." (PMID 32725768, 2020). "We observed that HCG18 overexpression resulted in a significant acceleration of tumor growth over time, with consistently larger tumor volumes." (PMID 40303288, 2025). "The lncRNA HCG18 captures miR-34a-5p, thereby upregulating RHAMM and advancing LUAD, underscoring the pivotal role of the HCG18/miR-34a-5p/RHAMM pathway in promoting LUAD tumor growth." (PMID 40806330, 2025). "The modulation of HCG18 expression level is expected to influence the anti-tumor activity of erastin, as indicated by the observed effects on ferroptosis." (PMID 40303288, 2025). "We observed a significant decrease in miR-30a-5p expression and a significant increase in RRM2 expression in tumor tissues with HCG18 overexpression." (PMID 40303288, 2025). "The average tumor weight of HCG18 ov group stayed the same trend, indicating that overexpression of HCG18 promoted tumor growth." (PMID 36854894, 2023). "The prior studies have addressed that lncRNA HCG18 positively promoted tumor growth, migration and invasion in vitro." (PMID 36854894, 2023). "For instance, lncRNA HCG18 overexpressed in hepatocellular carcinoma and promotes tumor development by regulating miR-214-3p/CENPM." (PMID 36854894, 2023). "All results suggested that overexpression of exosomal lncRNA HCG18 exerted its function in facilitating tumor development both in vitro and in vivo." (PMID 36854894, 2023). "The lung metastasis results showed that increasing HCG18 level accelerated tumor metastasis in comparison of NC group." (PMID 36854894, 2023). "MiR-424-5p, served as tumor suppressor, was a direct target of HCG18 and was negatively regulated by HCG18." (PMID 36854894, 2023). "Staining of tumor sections showed that Ki67 expression decreased and apoptosis rate increased in the HCG18-knockdown group compared with the control group." (PMID 34991445, 2022). "Our data revealed that the HCG18-overexpressed xenograft had a larger tumor size and tumor weight compared to the xenograft transfected with control lentivirus." (PMID 35389764, 2022). "It is worth mentioning that although HCG18 is linked to a better prognosis in our risk signature, its expression is higher in tumors compared to adjacent normal tissues, which may be due to the compensatory effect of this lncRNA as a potential tumor suppressor." (PMID 36105077, 2022). "The expression of HCG18 was positively correlated with the tumor stage and grade of lymph node dissemination (P< 0.05)." (PMID 35389764, 2022). "As a target gene of mir-34A-5p, HMMR can promote tumor growth in LUAD through the HCG18/Mir-34A-5p/HMMR axis." (PMID 35692818, 2022). "Silencing HCG18 reduced tumour size and levels of Ki67 and TRAF4/5 while increasing miR-29a/b levels in vivo." (PMID 34983361, 2022). "Overall, our study pioneered this field, and further investigations should be performed to fully reveal the function of HCG18 in EOC-associated fibroblasts and the tumour microenvironment." (PMID 34983361, 2022). "HCG18 expression was significantly higher in primary tumor tissues of HNSCC patients than in adjacent normal tissues (P< 0.001)." (PMID 35389764, 2022). "HCG18 levels in tumour tissues (n = 30) were increased compared to those in normal tissues (n = 30)." (PMID 34983361, 2022). "To explore the mechanism of HCG18 overexpression, we investigated the genomic characteristics of HCG18 in tumor samples." (PMID 34527669, 2021).
tumor (continued). "Expression of HCG18 was low in tumors overall, but relatively high in the mononuclear macrophage system, T cells, NK cells, and tumor stem cells." (PMID 34527669, 2021). "The tumor stem cell score based on the one-class logistic regression (OCLR) algorithm showed that HCG18 and its regulated transcription factors HMGA1, ILF2, and YBX1 positively correlated with the degree of tumor undifferentiation." (PMID 34527669, 2021). "At the same time, higher expression of HCG18, HMGA1, ILF2, and YBX1 was associated with a higher stem cell score and less tumor differentiation." (PMID 34527669, 2021). "In conclusion, the high expression of HCG18 indicates the increased sensitivity of tumor to immune checkpoint therapy." (PMID 34527669, 2021). "LncRNA HLA complex group 18 (HCG18) is characterized as a tumor-promoting lncRNA that plays critical roles in diverse human cancers." (PMID 34976998, 2021). "In conclusion, HCG18 can simultaneously evaluate tumor angiogenesis, invasion and immune microenvironment." (PMID 34527669, 2021). "In vivo assays revealed that reducing HCG18 expression in the BC cell line MDA-MB-231 markedly decreased tumor growth and lung metastasis in xenograft mouse models." (PMID 34976998, 2021). "According to TCGA, we searched HCG18 expression in multiple tissues and GC specimens and found that HCG18 was overexpressed in various cancer tissues in comparison with normal tissues especially in GC, which indicated tumor promoting role of HCG18." (PMID 32725768, 2020). "The mean value of relative expressions of HCG18 in tumor tissues (qRT‐PCR data) was used as the threshold, and then the specimens were separated into high expression group or low expression group." (PMID 32725768, 2020). "HCG18 is normally identified as a tumor differentiation regulating gene." (PMID 41300831, 2025). "To further verity the influence of HCG18 on tumor proliferation in vivo, we performed IHC on Ki67." (PMID 40303288, 2025). "Moreover, it is clear that HCG18 is dysregulated in many tumours and can predict the prognosis of certain tumours." (PMID 37085667, 2023). "In addition, we found cancer cell-secreted exosomes transitted HCG18 and accelerated surrounding tumor cells growth and metastasis." (PMID 36854894, 2023). "Knockdown HCG18 significantly reduced the average tumor weight compared to the si-NC group." (PMID 36854894, 2023). "Besides, we found cancer cell-secreted exosomes transitted HCG18 to surrounding tumor cells and accelerated tumor growth and metastasis." (PMID 36854894, 2023). "A previous study reported that HCG18 was highly overexpressed in lung adenocarcinoma and could facilitate tumour growth." (PMID 34983361, 2022). "Considering that HCG18 acts as a ceRNA to absorb multiple miRNAs and plays a role in tumour cells, we investigated whether there is a targeting relationship between HCG18 and miR-29a/b." (PMID 34983361, 2022). "HCG18 can also play tumor-promoting roles in many other types of cancers." (PMID 34976998, 2021). "HCG18 could promote BC cell proliferation and invasion, endow BC cells with CSPs in vitro, and facilitate tumor growth and metastasis in vivo." (PMID 34976998, 2021). "Our in vivo research validated that HCG18 knockdown suppressed tumor growth and distal MTS." (PMID 32725768, 2020). "In addition, the data demonstrated that HCG18 might sponge miR-424-5p to enhance the tumorigenesis, metastasis in vivo and miR-424-5p was the possible tumor suppressor." (PMID 36854894, 2023). "Inhibition of HCG18 or RRM2, or activation of miR-30a-5p significantly decreased the tumor growth, but markedly increased the Fe2+ and MDA induced by erastin in tumor tissues." (PMID 40303288, 2025). "In contrast to the control vector group, the overexpression of HCG18 markedly reduced the increase in Fe2+ and MDA induced by erastin in tumor tissues." (PMID 40303288, 2025).
tumor (continued). "Both HCG18 and hsa_circ_0005273 act to increase RHAMM expression, thereby contributing to tumor growth and increased cell proliferation." (PMID 40806330, 2025). "Considering our data in EOC cells, HCG18 and TRAF4 are potential regulators of the tumour microenvironment in EOC." (PMID 34983361, 2022). "Among them, FAM30A, HCP5, LINC00963, TMEM147-AS1, and TTTY15 indicated a worse prognosis, but LINC00342, MEG3, HCG18, and N4BP2L2-IT2 demonstrated a better tumor prognosis." (PMID 35615374, 2022). "HCG18 is involved in vascular invasion of HCC through regulation of macrophages and tumor stem cells." (PMID 35627170, 2022). "We found that HCG18 expression level in EOC tissues was significantly higher in high tumour stage (III–IV) and tumour grade (G3)." (PMID 34983361, 2022). "HCG18 participates in vascular invasion of HCC by regulating macrophages and tumor stem cells through three key transcription factors, YBX1, ILF2, and HMGA1." (PMID 34527669, 2021). "Also, it has been shown that HCG18 knockdown in GC cell lines AGS and MKN-28 decreased tumor proliferation, migration, and invasion, and suppressed tumor growth and metastasis." (PMID 38226210, 2024). "For instance, HCG18, PVT1, and LINC02381 are highly expressed in BC and expedite tumor progression." (PMID 37304675, 2021). "Furthermore, a positive correlation was found between HCG18 or RRM2 expression and tumor stage." (PMID 40303288, 2025). "RNASeq and scRNASeq showed that overall expression of HCG18 was not high in tumors, but was specifically distributed in mononuclear macrophages and tumor stem cells, which were identified as being key to vascular invasion based on cellular communication analysis." (PMID 34527669, 2021). "Mononuclear macrophages and tumor stem cell-like cells in the VEGF pathway are the core cells, while cells related to the VEGI pathway are not related to HCG18 and its regulation of transcription factor expression." (PMID 34527669, 2021).
cancer (20 papers, 2016 to 2025). A tumor composed of atypical neoplastic, often pleomorphic cells that invade other tissues. "All these achievements indicated that HCG18 may be a potential diagnostic marker and a novel antitumor target for cancer therapy." (PMID 34976998, 2021). "High expression levels of HCG18, ILF2, YBX1, and HMGA1 are strongly positively associated with cancer stem cells." (PMID 40055311, 2025). "Recent studies have suggested that HCG18 plays a pivotal role in various cancers by influence different miRNA." (PMID 40303288, 2025). "Functional experiments affirm the cancer-promoting role of HCG18, influencing cell viability, migration, and invasion as well as the EMT process in QBC939 cells." (PMID 39161590, 2024). "LncRNA HLA complex group 18 (lncRNA HCG18) has been recognized as a cancer-promoting gene in various cancers by existing researches." (PMID 36854894, 2023). "To explore miR-424-5p biological function in cancer development and biological interaction with HCG18, we conducted several rescue experiments in three groups with different transfections in QBC939 cells." (PMID 36854894, 2023). "Collectively, the data demonstrated that LncRNA HCG18 was transmitted through exosomes in cancer cells." (PMID 36854894, 2023). "Next, we investigated the impact of exosomal lncRNA HCG18 on cancer cells development via several functional experiments." (PMID 36854894, 2023). "Flow cytometry results pointed that increasing HCG18 level reduced cancer cells apoptosis ability compared to control group." (PMID 36854894, 2023). "In order to further understand the function and regulatory role of lncRNA HCG18, it is necessary to understand its localization and distribution in cancer cells." (PMID 36854894, 2023). "In most cancers, HCG18 is up-regulated and exerts its oncogenic effects by regulating cancer cell proliferation, migration, invasion and apoptosis." (PMID 37884975, 2023). "In vitro experiments like (CCK-8, EdU, colony formation, flow cytometry, transwell, wound healing assays) and animal study confirmed that lncRNA HCG18 served as a cancer-promoting gene, promoted cancer proliferation, migration and invasion abilities." (PMID 36854894, 2023). "LncRNA HCG18 (HLA Complex Group 18) participates in the biological development of several types of cancers." (PMID 37884975, 2023). "In a word, the results demonstrated that overexpression of SOX9 altered the repression of cancer cell mediated by lncRNA HCG18 knockdown through PI3K/AKT pathway." (PMID 36854894, 2023). "FGD5-AS1 and HCG18 are predicted to sponge several miRNAs of cancer cells to promote cancer proliferation." (PMID 37190145, 2023). "In the meanwhile, up-regulation of HCG18 also led to a positive impact on promoting cancer cells migration and invasion through wound healing and tranwell assays." (PMID 36854894, 2023). "We further revealed the regulation of cytokines and inflammatory pathways by HCG18 in cancer cells for the first time, which functions by inhibiting the expression of miR-29a/b as a ceRNA." (PMID 34983361, 2022). "Various studies have suggested that HCG18 is involved in a variety of human diseases, including diabetic peripheral neuropathy, intervertebral disc degeneration and cancer." (PMID 34983361, 2022). "We found that AC090425.1 and HCG18 were related to a variety of cancer-related pathways, while TTC28-AS1 and LINC00092 were related to diverse cancer functions." (PMID 34615480, 2021). "To investigate the effect of HCG18 on immune checkpoint therapy, we performed a pan cancer analysis based on TCGA." (PMID 34527669, 2021). "Taken together, these results confirmed that UBE2O plays a vital role in the cancer-promoting function of HCG18 in BC cells." (PMID 34976998, 2021). "Pan cancer analysis indicated that high expression of HCG18 implies high sensitivity to immune checkpoint therapy." (PMID 34527669, 2021).